VWF (von Willebrand factor)
Diseases named in the same sentence as VWF in open-access papers (continued):
Sharing a sentence is not in itself a finding about the gene and the disease.
COVID-19 (continued). "These analyses suggest that VWF parameters (i.e., the VWF/ADAMTS13 activity ratio) and thrombin and plasmin generation differed in COVID-19 (+), as compared to COVID-19 (−) patient plasma." (PMID 35087853, 2021). "The median VWF:AG level, VWF: CBA, and VWF:AG/ADAMTS13 activity ratio were all increased in COVID-19 (+) patients, as compared to the acutely ill COVID-19 (−) cohort." (PMID 35087853, 2021). "Specifically, in the COVID-19 (+) group, median VWF:AG, VWF: CBA and VWF:AG/ADAMTS13 activity ratios increased (by 43, 23, and 21.5%, respectively) compared to the COVID-19 (−) group." (PMID 35087853, 2021). "We examined the levels of platelets, D-dimers, FVIII, vWF antigen, and ADAMTS13 in critically ill patients with established COVID-19 admitted to ICU." (PMID 34476137, 2021). "The VWF/ADAMTS13 axis as well as plasma hemostasis and fibrinolysis were compared within the COVID-19 (−) and COVID-19 (+) groups to understand the differences in VWF/ADAMTS13 axis and plasma coagulopathy between surviving and non-surviving patients." (PMID 35087853, 2021). "Our data add to the findings on various markers of endothelial cell and platelet activation, including vWf, soluble thrombomodulin, soluble CD40 ligand, and plasminogen activator inhibitor (PAI)-1, studied in COVID-19." (PMID 33477776, 2021). "Large increases of von Willebrand factor (VWF) and factor VIII activity has also been observed in COVID-19, which is also attributed to endothelial damage." (PMID 33102511, 2020). "Increased D-dimer levels, CRP, Factor VIII, vWF, fibrin degradation product (FDP), longer PT, and activated partial thromboplastin time (APTT) was observed in critically ill COVID-19 patients." (PMID 33193350, 2020). "In this review, we summarize the biological characteristics and interactions of NETs, VWF, and ADAMTS13, and discuss their roles in TMAs, AIS, and COVID-19." (PMID 33343584, 2020). "In non-pregnant individuals, distinct COVID-19-related hemostasis and fibrinolysis laboratory findings, including the increase in D-dimer and VWF levels, and decrease in FXIII levels have been well-known and described in detail in the literature." (PMID 40303405, 2025). "Although the presence of ultra-large vWF (ULvWF) multimers has not been directly demonstrated in COVID-19 patients, it is widely accepted that an excess of HMvWF relative to normal plasma promotes a prothrombotic state." (PMID 40508203, 2025). "Early investigations reported much higher antigen levels and von Willebrand factor (vWF) activity between ICU and non-ICU COVID-19 patients, which were inversely associated with PaO2/FiO2 values." (PMID 38276214, 2024). "However, in patients with COVID-19, the expression of ITGAM, vWF, and PLEK was higher when compared with ECs of healthy patients." (PMID 39066212, 2024). "In addition, reduced levels of the specific vWF-cleaving protease ADAMTS 13 (a disintegrin and metalloprotease with a thrombospondin type 1 motif member 13) have been described in COVID-19." (PMID 38732160, 2024). "Also, in COVID-19 patients, increased levels of ICAM-1, VCAM-1, VEGF, VWF, and TF in serum and plasma are observed which correlate with the severity of the disease." (PMID 39457048, 2024). "In comparison with our data in the failing human heart due to cardiomyopathies, coronary vascular microthrombi in COVID-19 patients is not dependent on endothelial cell activation assessed by expression of endothelial adhesion molecules or VWF." (PMID 38381272, 2024). "Because of the lack of significant differences in the distribution of VWF and fibrin between COVID-19 and non–COVID-19 hearts, heart tissue samples were not further stained for CD42b." (PMID 37333991, 2023). "Several factors such as soluble TNF receptor II (TNFRSF1B) and von Willebrand factor (VWF) were found to increase with COVID-19 regardless of pregnancy status." (PMID 37016066, 2023).
COVID-19 (continued). "When analyzed for VWF, capillary microthrombi were found in 50% of the patients with COVID-19 vs 44% of the controls, which was not significantly different." (PMID 37333991, 2023). "The maintenance of the equilibrium of vWF and its specific cleaving protease ADAMTS13 is a limiting factor in the process of microthrombosis, and the equilibrium is disturbed in systemic inflammation such as also severe COVID-19." (PMID 36768817, 2023). "The activation of the complement system was documented in COVID-19 with the formation of the terminal membrane attack complex (MAC) that, in turn, can activate platelets with subsequent endothelial damage and the secretion of VWF." (PMID 37240292, 2023). "To sum up, we found that the expression of Ang1, VEGF, and VWF was regardless of the presence or absence of active lymphocytic myocarditis in 15 patients deceased during the first wave of COVID-19." (PMID 37175037, 2023). "Accentuated capillary VWF staining was not exclusive to COVID-19 samples but was found in 29% of the controls." (PMID 37333991, 2023). "Von Willebrand factor polymerizes into large multimers that are size regulated by ADAMTS-13 (A Disintegrin And Metalloprotease with ThrombSpondin Motif type 1 motif, member 13), which is reduced in severely ill COVID-19 patients." (PMID 37448794, 2023). "Similarly in COVID-19 patients, the prothrombotic state is confirmed by increased levels of D-dimer, fibrinogen, factor VIII (FVIII), von Willebrand factor (vWF) and decreased antithrombin." (PMID 36158866, 2022). "It is assumed that the imbalance between vWF and ADAMTS-13 in COVID-19, including a decrease in the level and activity of ADAMTS-13, may create microthrombotic conditions leading to secondary thrombotic microangiopathy." (PMID 35887770, 2022). "COVID-19 patients with hypoxia appear to be suffering from prothrombotic conditions, through the upregulation of PAI-1 and the stimulation of procoagulants synthesis, like TF and von Willebrand Factor (vWF)." (PMID 36295093, 2022). "In this study, we looked closely at the role of vWF and ADAMTS-13 in COVID-19." (PMID 35887770, 2022). "Elevated levels of established risk factors for thrombosis, in particular elevated levels of VWF and decreased levels of ADAMTS-13 which suggests endothelial activation, may be considered in the treatment of COVID-19." (PMID 35482749, 2022). "However, other coagulation parameters such as fibrinogen, vWF, and factor VIII activity in COVID-19 are distinct from those in DIC." (PMID 36013974, 2022). "Comparing thrombus composition of COVID-19 and control patients, we noted no overt differences in terms of red blood cells, fibrin, neutrophil extracellular traps (NETs), von Willebrand Factor (vWF), platelets and complement complex C5b-9." (PMID 35105380, 2022). "In this regard, studies reported that COVID-19 nonsurvivors have shown higher VWF and lower ADAMTS13 compared with survivors." (PMID 36128671, 2022). "It has been hypothesised that the imbalance of VWF and ADAMTS-13 in COVID-19 may promote multi-organ thrombosis with a clinical picture of thrombotic microangiopathy." (PMID 35189860, 2022). "Furthermore, von Willebrand factor (VWF) and factor VIII activities are significantly increased in COVID-19 patients." (PMID 35215822, 2022). "Similarly, mean levels of fibrinogen, D-dimer, and von Willebrand factor (VWF) were shown to be significantly increased in a study conducted in Milan, Italy, on COVID-19 patients in the intensive care unit (ICU)." (PMID 33923537, 2021). "Non-ICU patients with COVID-19 were found to have elevated von Willebrand factor (vWF) levels and activity as well as D-dimer and thrombin-antithrombin levels above the normal range, which were further increased in ICU patients." (PMID 33499234, 2021). "Elevated VWF antigen and activity levels have been documented in COVID-19.9, 11, 20Likewise, inflammatory markers such as CRP and IL-6 are known to be elevated in COVID-19." (PMID 33709050, 2021).
COVID-19 (continued). "However, biomarkers of endothelial damage, such as thrombomodulin, vWF, angiopoietin 2, and PAI1, are often elevated in COVID-19 patients, and have prognostic relevance." (PMID 34451848, 2021). "Based on our current data with COVID-19 (−) and COVID-19 (+) patients, there was a clear age-dependent effect (i.e., ≥65) on VFW:AG, VWF collagen binding activity, and the VWF:AG/ADAMTS13 activity ratio, suggesting an enhanced potential for endothelial coagulopathy." (PMID 35087853, 2021). "Independent of COVID-19, VWF:AG and the VWF:AG/ADAMTS13 activity ratio increase with aging (≥65 years of age) and body mass index (BMI; >25 kg/m2)." (PMID 35087853, 2021). "Persistently elevated levels of VWF have also been shown in both critically ill and non-critically ill COVID-19 patients." (PMID 33378321, 2021). "At the time of the initial blood draw, hospitalized COVID-19 (−) patients who ultimately did not survive their illness demonstrated significantly (p < 0.05) higher VWF levels and collagen binding activity as well as higher FVIII levels compared to COVID-19 (−) patients who survived their illness." (PMID 35087853, 2021). "The VWF:AG/ADAMTS13 activity ratio was increased by 32 vs. 23% in COVID-19 (−) and COVID-19 (+) non-surviving patients, respectively." (PMID 35087853, 2021). "In summary, we present the most comprehensive and largest study to date analyzing correlations of D-dimer levels with VWF activity and antigen, size of VWF multimers, ADAMTS13 activity levels, markers of intravascular hemolysis, and smear pathology in hospitalized COVID-19 patients." (PMID 33709050, 2021). "Comparisons between the two age groups within the COVID-19 (+) patients indicates that patients ≥65 years of age have a reduced plasma ADAMTS13 activity (remaining in the reference range), as well as increased VWF:AG, VWF:CBA, and VWF/ADAMTS13 activity ratio." (PMID 35087853, 2021). "Our results indicate that in our cohort, ICU admission levels of soluble E-selectin, sP-selectin, Ang-2, sICAM-1, and vWf are higher in COVID-19 critically ill patients who will not survive." (PMID 33477776, 2021). "This is relevant given the importance of coagulopathy in COVID-19, with increased plasma levels of FVIII, D-dimers, and VWF (i.e., increased VWF:collagen-binding activity, increased VWF:ADAMTS-13 activity ratio), which are among the top correlates of mortality in our cohort." (PMID 34571942, 2021). "Further, the deep plasma proteome study of non-severe versus severe COVID-19 patients revealed only 38 differentially expressed proteins, out of which proteins such as FGG, S100A8, VWF, SAA4, SERPIND1, and SERPINA6 were identified to be significantly upregulated in the COVID-19 severe patients." (PMID 33995121, 2021). "Although measurement of VWF level and activity are not common practice in the clinical setting, these data support that the coagulopathy of COVID-19 results, in part, from widespread endothelial injury." (PMID 33378321, 2021). "Von Willebrand Factor (VWF), a pro-adherent glycoprotein released from activated endothelial cells due the endothelial injuries, is significantly elevated in plasma COVID-19 patients compared to normal individuals, thus predicting a risk of arterial thrombosis." (PMID 34360751, 2021). "In addition to ACE2, another crucial pro-coagulant factor, von Willebrand factor (VWF), is upregulated in COVID-19 patients." (PMID 32486196, 2020). "Along with NETs, VWF and ADAMTS13 are also reported to be involved in COVID-19." (PMID 33343584, 2020). "Additionally, von Willebrand factor (VWF), a marker of endothelial activation is also increased in CRS and has been described in COVID-19 patients." (PMID 33149733, 2020). "Although the involvement of NETs and VWF in endothelial damage and COVID-19 has been elucidated, no direct evidence yet demonstrates their interactions contributing to COVID-19 progression." (PMID 33343584, 2020).
COVID-19 (continued). "In terms of biological mechanistic insights, pulmonary endothelial-cells of non-O blood groups are associated with higher VWF protein compared to O-group, accounting for the role that the GWAS ascribed to the ABO-locus in COVID-19." (PMID 32899439, 2020). "Interestingly, even non-critically-ill COVID-19 patients exhibit increased vWF levels compared with healthy controls, highlighting the systemic nature of COVID-19-induced coagulopathy." (PMID 40002898, 2025). "Interestingly, despite the changes in F8 levels, VWF was significantly lower in PLWH with COVID-19 than in PLWH, while PROC did not change significantly." (PMID 40568587, 2025). "Another study revealed a significant increase in vWF activity and decreased ADAMTS-13 levels in COVID-19 patients, suggesting that impaired regulation of vWF and the reduced capacity of its cleavage by ADAMTS-13 could be indicative of an increased thrombosis risk." (PMID 40612950, 2025). "Importantly, vWF collagen-binding activity (vWF-CBA), rather than vWF antigen (vWF:Ag) or ristocetin cofactor activity (vWF:RCo), showed a significant correlation with COVID-19 disease severity." (PMID 40508203, 2025). "Interestingly we also observed an increase in vWF deposition in the extracellular matrix by endothelial cells that had undergone treatment with COVID-19 or ARDS serum but not by those treated with control serum." (PMID 38041432, 2024). "In addition, autopsies of COVID-19 patients who died of acute respiratory distress syndrome revealed numerous intrapulmonary arteriole thrombi, including fibrin, CD61-positive platelets and megakaryocytes, with positive immunostaining of vWF." (PMID 36982387, 2023). "Moreover, deceased COVID-19 patients (n = 25) showed the greatest increase in serum vWF levels, as compared to hospitalized COVID-19 patients with (n = 33) and without oxygen therapy (n = 27)." (PMID 36941580, 2023). "Of note, vWF was also increased in non-critically ill COVID-19 patients compared to controls." (PMID 36851722, 2023). "In addition, VWF Antigen (VWF:Ag) in his patients was significantly higher compared to non-COVID-19 patients and in critical patients to non-critical patients." (PMID 36138306, 2023). "Corticosteroids may have a direct effect on coagulation pathways including reductions in VWF and fibrinogen levels, which have not been evaluated in COVID-19 patients." (PMID 37987325, 2023). "Similarly, ADAMTS13 levels were reduced (p = 0.009) and the VWF/ADAMTS13 ratio was increased (p = 0.0004) in convalescent COVID-19 patients with dysregulated angiogenesis and immunothrombosis, while levels of PF4 (a putative protector of VWF) were also elevated (p = 0.0001)." (PMID 36926331, 2023). "Several inflammatory mediators, such as ENPP2, C5, FASLG, VWF, and CSF1, additionally presented a more robust correlation with the core inflammatory networks in the severe group, and these factors were reported as independent significant indicators of severe COVID-19 in previous studies." (PMID 36776879, 2023). "However, the robust study design and statistical analysis as well as the consistencies with previous studies, such as the upregulation in patients with COVID-19 of ACE2, FGF21, CCL26 and VWF among others, suggest the potential validation of these novel findings." (PMID 37047248, 2023). "However, VWF+ thrombi were detectable in 39% of the patients with COVID-19 but, in contrast to fibrin thrombi, in none of the controls." (PMID 37333991, 2023). "Furthermore, when assessed for VWF, accentuated capillary, ie, endothelial, VWF staining was not exclusive to COVID-19." (PMID 37333991, 2023). "However, severe COVID-19 patients who died in ICU (n = 3) had significantly higher vWF levels at ICU admission that did not decrease during hospitalization, although these findings were based on low patient numbers." (PMID 36941580, 2023).
COVID-19 (continued). "Notably, we found a similar association between respiratory dysfunction and the coagulation response, in that several markers, i.e., vWF, Thrombomodulin, Factor XII, and Factor VIII; correlated with respiratory SOFA and PaO2/FiO2 ratio solely in COVID-19 patients." (PMID 36829233, 2023). "Another study indicated that among ICU patients with COVID-19, levels of endothelium biomarkers (such as soluble E-selectin, soluble P-selectin, angiogenin (Ang) 2, soluble intercellular adhesion molecule-1, and vWF) were higher in non-survivors." (PMID 36248790, 2022). "We did find that VWF pro-peptide was significantly increased in subjects with a history of COVID-19 compared to controls (+ 30.7%, p < 0.0001) and compared to vaccinated subjects without prior COVID-19 (+27.8%, p < 0.0001)." (PMID 35966540, 2022). "Thrombosis as well as elevated circulating levels of coagulation-promoting factors such as von Willebrand factor (VWF) and pro-inflammatory cyto/chemokines including angiopoietin-2 suggest that severe COVID-19 in part should be considered an endothelial disease (Libby and Lüscher, 2020)." (PMID 35452595, 2022). "Therefore, it is not surprising that vWF /ADAMTS13 axis can be involved in the thrombotic microangiopathy observed during COVID-19 outside pregnancy." (PMID 35189860, 2022). "Thus, the elevated VWF and FVIII levels in COVID-19 indicate the state and degree of inflammation." (PMID 35996516, 2022). "Specifically, VWF, F13A1 (factor XIII A subunit), F13B (factor XIII B subunit), FGA (alpha subunit of fibrinogen), FGB (beta component of fibrinogen), GP1BA (glycoprotein Ib-alpha)—were all procoagulant proteins and/or of platelet origin enriched in both LEVs and SEVs from COVID-19 (+) patients." (PMID 36564503, 2022). "The elevated levels of vascular endothelial activation markers, including von Willebrand factor (VWF), plasminogen activator inhibitor, intercellular adhesion molecule-1 (ICAM-1), and vascular cell adhesion molecule-1 (VCAM-1), have been observed in patients with COVID-19." (PMID 36551272, 2022). "However, in most studies, the plasma levels of VWF were measured, which did not allow objective assessment of the role of endothelial VWF in the thrombosis development in COVID-19." (PMID 35215805, 2022). "In a retrospective observational study, persistent endotheliopathy with increased levels of factor VIII, VWF, and thrombomodulin, compared with healthy subjects, was observed in convalescent COVID-19 patients, independent of ongoing acute phase response or NETosis." (PMID 34769508, 2021). "In addition, the levels of VWF and ADAMTS13 can predict the mortality of COVID-19." (PMID 33343584, 2020). "The interplay among NET, VWF and ADAMTS13 might form a vicious cycle, resulting in reduced ADAMTS13 activity and subsequently elevated plasma levels of VWF, which is positively correlated with severity and mortality in TMAs, AIS, and COVID-19." (PMID 33343584, 2020). "Von Willebrand Factor’s effects during COVID-19-associated coagulopathy does not appear unique to the virus, but rather to the presence of inflammation, as other conditions such as sepsis, DIC, cancer, and malaria also show marked effects on the von Willebrand Factor." (PMID 38745860, 2024). "Moreover, platelets exhibited hyperresponsive behavior with increased aggregation and adhesion response, which might be linked to increased expression of adhesive receptors, such as von Willebrand factor (VWF) and fibrinogen receptors, GPIbα/GPIX and GPIIb/III, identified in patients with COVID-19." (PMID 35982454, 2022). "In a sense, acquired TTP is caused by an abnormal ratio of vWF, which may be released in normal quantities, and nonfunctioning ADAMTS13, whereas in COVID-19, there is a massive release of ULvWF and regular or reduced levels of ADAMTS13, secondary to consumption, that result in microthrombosis." (PMID 34208470, 2021).